TMEM164 (transmembrane protein 164)
Description:
Positive regulator of ferroptosis. Involved in the acylation of ether lysophospholipids with the arachidonoyl chain (5Z,8Z,11Z,14Z-eicosatetraenoyl; C20:4) of diacylglycerophospholipids, generating C20:4 ether glycerophospholipids (ePEs) such as 1-(1Z-octadecenyl)-2-(5Z,8Z,11Z,14Z-eicosatetraenoyl)- sn-glycero-3-phosphoethanolamine (PE (P-18:0/20:4)), which promotes ferroptosis. Selectively mediates ATG5-dependent autophagosome formation during ferroptosis, rather than during starvation, and regulates the degradation of ferritin, GPX4 and lipid droplets to increase iron accumulation and lipid peroxidation, thereby promoting ferroptotic cell death.
Synonyms: FLJ22679; RP13-360B22.2; bB360B22.3
Tractability: Antibody: UniProt predicts a signal peptide or a membrane-spanning region. PROTAC: ubiquitination databases record sites on it.
Gene: Protein-coding gene on chromosome X (110,002,631 to 110,184,260, forward strand). Ensembl gene ENSG00000157600.
Subcellular location: Membrane
Subcellular location (Human Protein Atlas): Vesicles; Cell Junctions
Gene Ontology:
Biological process: positive regulation of ferroptosis
Cellular component: membrane
Homologues: Orthologues: chimpanzee TMEM164 (99% identical), dog TMEM164 (98% identical), pig TMEM164 (98% identical), rat Tmem164 (96% identical), mouse Tmem164 (95% identical), guinea pig TMEM164 (94% identical), macaque TMEM164 (91% identical), rabbit TMEM164 (72% identical), tropical clawed frog tmem164 (70% identical), zebrafish TMEM164 (64% identical), Drosophila melanogaster CG14591 (35% identical), Caenorhabditis elegans C35C5.10 (34% identical).
Diseases named in the same sentence as TMEM164 in open-access papers:
TMEM164 is named in the same sentence as 5 diseases in open-access papers, as found by Europe PMC text mining. Sharing a sentence is not in itself a finding about the gene and the disease. The quoted sentences say what the papers report.
pancreatic cancer (4 papers, 2023 to 2024). "Moreover, in pancreatic cancer, transmembrane protein 164 (TMEM164) has been shown to activate autophagy, leading to the degradation of ferritin, GPX4, and lipid droplets." (PMID 39867656, 2024). "Up-expressed TMEM164 in pancreatic cancer may improve survival and reshape TIME." (PMID 37373430, 2023).
lung carcinoma (1 paper, 2024). "TMEM164, classified as a member of the transmembrane protein (TMEM) family, is characterized by its presence in various biological membranes and its independent influence on lung carcinoma prognosis." (PMID 38495502, 2024).
steatosis (1 paper, 2024). Increased lipid within the cytoplasm of cells. "TMEM164 has been shown to promote steatosis via regulation of oxidative stress through calcium-activated chlorine channels and is up-regulated in patients and mice with NAFLD40." (PMID 38336825, 2024).
tumor (3 papers, 2021 to 2026). "In addition, TMEM164 loss attenuates the anti-tumor response of ferroptosis-induced cytotoxicity." (PMID 37373430, 2023). "Among these mRNAs, TMEM164, ZNF607, and ANKRD13B showed significant altered expression across tumor stages, indicating their role in cancer progression and invasion." (PMID 35140741, 2021). "Compared with non-tumor lung tissues and the normal human bronchial epithelial cell line BEAS-2B, TMEM164 expression is markedly reduced in LUAD tumors and in the LUAD cell lines A549 and NCI-H358, as verified in both the Human Protein Atlas (HPA) database and clinical specimens." (PMID 41596760, 2026). "Additionally, TMEM164 expression enhances the efficacy of anti-PD-1 (programmed cell death protein 1) therapy in mouse models, where combination treatment leads to suppressed tumor growth without affecting body weight." (PMID 41596760, 2026).
cancer (2 papers, 2021 to 2026). A tumor composed of atypical neoplastic, often pleomorphic cells that invade other tissues. "It worth noting that for LIHC, combinations of prognostic values of SNHG20 lncRNA and BUB1 mRNA, and also SNHG12 lncRNA and TMEM164 mRNA (associated with reduced OS with worse prognosis), could strengthen the predictive value of these markers for this cancer." (PMID 35140741, 2021). "Our study found that in ceRNA networks of LIHC, combination of prognostic values of SNHG20 lncRNA and BUB1 mRNA, and also SNHG12 lncRNA and TMEM164 mRNA (associated with reduced OS with worse prognosis), could be used as collective prognostic values for this cancer." (PMID 35140741, 2021).